CYP1B1 (cytochrome P450 family 1 subfamily B member 1)
Diseases named in the same sentence as CYP1B1 in open-access papers (continued):
Sharing a sentence is not in itself a finding about the gene and the disease.
glaucoma (108 papers, 2007 to 2025). Increased pressure in the eyeball due to obstruction of the outflow of aqueous humor. "In humans, CYP1B1 mutations have been shown to be modified by PITX2, with CYP1B1-related juvenile glaucoma patients carrying the PITX2P179T allele developing earlier onset glaucoma than their PITX2wt relatives." (PMID 41011222, 2025). "Numerous genes and genetic changes have been described in association with childhood glaucoma, with the most common being CYP1B1, MYOC, and FOXC1." (PMID 38386645, 2024). "The variant c.83C>G (p.S28W) in the CYP1B1 gene was identified in a 66-year-old male patient, diagnosed with myopia magna and moderate glaucoma at the age of 60." (PMID 38241218, 2024). "We performed an initial study to identify pathogenic variants in the MYOC and CYP1B1 genes, which were the only fully-described glaucoma-causing genes at that time." (PMID 38241218, 2024). "Myocilin and cytochrome P450 1B1 (CYP1B1): Myocilin was the first gene identified to be linked to glaucoma." (PMID 38435218, 2024). "Congenital Glaucoma can be caused by the CYP1B1, LTBP2, TEK, and two loci of uncertain function which were not investigated in this research." (PMID 39480826, 2024). "Several genes and/or loci are reported to be causative and are referred to as GLC (glaucoma) loci; for example, CYP1B1 is located at the GLC3A locus (2p21), and LTBP2 is located at the GLC3D locus (14q24.3)." (PMID 39158757, 2024). "Cyp1b1 deletion in mice also led to structural abnormalities in the eye with loss of collagen, resulting in glaucoma." (PMID 37442234, 2023). "List of some pathogenic/likely pathogenic glaucoma-associated CYP1B1 missense mutations (Source: gnomAD browser)." (PMID 38152303, 2023). "Cluster 2 also differentially expressed glaucoma gene CYP1B1, morphogen-encoding genes LEFTY2, FGF9, and FGF8." (PMID 37665325, 2023). "At least 82 mutations have been identified in CYP1B1 and are associated with various forms of glaucoma." (PMID 35295218, 2022). "Mutations correlating with various types of glaucoma have been identified in CYP1B1 and cause a low CYP1B1 enzymatic activity or its absence." (PMID 35743162, 2022). "CYP1B1 is highly expressed in many types of cancers, and its mutated alleles are detected in cancer and glaucoma." (PMID 36230892, 2022). "Primary congenital glaucoma (PCG) is the most common subtype of glaucoma caused by defects in the cytochrome P450 1B1 (CYP1B1) gene." (PMID 36518267, 2022). "CYP1B1, an AhR-inducible gene, is associated with various types of glaucoma, including two main ones: primary open-angle glaucoma and primary congenital glaucoma." (PMID 35743162, 2022). "In 8 (33%) children with childhood glaucoma one of the following congenital glaucoma associated genes (CYP1B1, FOXC1, LTBP2 and TEK) was confirmed by the genetic examination." (PMID 35144644, 2022). "CYP1B1 is a protein-coding gene, and diseases associated with CYP1B1 include glaucoma 3A, primary congenital, and anterior segment dysgenesis." (PMID 36239105, 2022). "In a study using the Adverse Outcome Pathway framework, the AHR is linked with glaucoma, including changes in the gene for CYP1B1." (PMID 35295218, 2022). "Remarkable phenotypic variability is also present in CYP1B1-associated glaucoma, ranging from mild adult-onset goniodysgenesis to agenesis of the Schlemm canal and complete aniridia." (PMID 34208498, 2021). "So far, several GWAS studies of glaucoma have identified over 100 risk loci, including mutations in the CYP1B1, OPTN, and PLEKHA7 genes." (PMID 34834521, 2021). "CYP1B1 is associated with glaucoma, and mutations in this gene in mice are associated with increases in IOP, oxidative stress and TM dysgenesis." (PMID 34440692, 2021). "Mutations in the cytochrome P450-1B1 (Cyp1b1) gene is a common genetic predisposition associated with various human glaucomas, most prominently in primary congenital glaucoma (PCG)." (PMID 33748124, 2021).
glaucoma (continued). "High-advanced technologies, including whole-exome sequencing (WES) and whole-genome sequencing (WGS), helped to reveal the molecular mechanisms of how genetic abnormalities such as CYP1B1 mutations lead to glaucoma and cancer." (PMID 32626511, 2020). "An important gene that is defective in patients with glaucoma is CYP1B1, a gene associated with optic nerve deterioration." (PMID 32626511, 2020). "Gong B., Qu C., Li X., Shi Y., Lin Y., Zhou Y., Shuai P., Yang Y.,Liu X., Zhang D., Yang Z. Mutation spectrum of CYP1B1 in Chinese patients with primary open-angle glaucoma." (PMID 35087999, 2020). "Lobov S.L., Khasanova R.R., Zagidullina A.S., Zaydullin I.S., Dzhemileva L.U., Khusnutdinova E.K. Analysis mutations CYP1B1 gene inpatients of hereditary forms of glaucoma." (PMID 35087999, 2020). "For example, cyp1b1, known to be associated with glaucoma predisposition, was identified in cluster 2, while tgfbi, isolated in cluster 4, is associated with corneal dystrophy." (PMID 32528955, 2020). "Null CYP1B1 mutations are the predominant known genetic cause of this type of glaucoma in different worldwide populations, and LTBP2 gene alterations have been identified only in a few families." (PMID 30657791, 2019). "We also evaluated the possible modifier role of FOXC2 and PITX2 defects on patients with CYP1B1 glaucoma-associated genetic backgrounds." (PMID 30657791, 2019). "To investigate possible oligogenic inheritance involving FOXC2 or PITX2 and CYP1B1, we also analyzed FOXC2 and PITX2 variants in a group of 25 CG cases who were known to carry CYP1B1 glaucoma-associated genotypes." (PMID 30657791, 2019). "The detailed information of glaucoma cases with mutations in CYP1B1 indicating their genotypes, phenotypes, age of onset, sex, ethinicity and geographical location." (PMID 30788381, 2018). "In India, mutations in Cytochrome P450 (CYP1B1) are a predominant cause of not only primary congenital glaucoma (PCG) but also involved in primary open angle glaucoma (POAG) and juvenile onset glaucoma (JOAG)." (PMID 30788381, 2018). "It has been demonstrated that glaucoma-associated CYP1B1 mutations reduce the enzymatic activity or stability of the enzyme and diminish the localization of the protein in the mitochondria." (PMID 28448622, 2017). "Exclusion of pathogenic variations in known glaucoma genes as CYP1B1, MYOC, FOXC1, PITX2 and PAX6 was additionally done per Sanger sequencing and Multiple Ligation-dependent Probe Amplification (MLPA) analysis." (PMID 27484908, 2016). "Mutations in CYP1B1 result in primary congenital glaucoma (PCG) by an autosomal recessive mode of inheritance while it acts as a modifier locus for primary open angle glaucoma (POAG)." (PMID 27243976, 2016). "We propose that the heterozygous parents of a PCG-affected child due presence of two defective alleles of CYP1B1 are prone to late onset glaucoma due to altered metabolizing activity of 17β-estradiol relative to the normal levels." (PMID 27243976, 2016). "Our results are also consistent with the observation that a mutation in a single allele of CYP1B1 induces late onset glaucoma (i.e. POAG) due to the lower steroid metabolism of the mutant allele." (PMID 27243976, 2016). "Loss-of-function CYP1B1 mutations are the predominant known genetic cause of this type of glaucoma in different populations." (PMID 25786029, 2015). "Our results for p.Arg368His, and in general for double heterozygotes for CYP1B1 mutations, suggest a more severe phenotype for glaucoma when a null allele due to a nonsense mutation is present." (PMID 23922489, 2013). "From these reports, it appears that CYP1B1 has a larger role to play in glaucoma pathogenesis, which includes causation of PCG, acting as a modifier for POAG and on rare occasions, being the primary cause of JOAG." (PMID 23028769, 2012).
glaucoma (continued). "Mutations in CYP1B1 have also been reported in primary open angle glaucoma (POAG) cases and suggested to act as a modifier of the disease along with Myocilin (MYOC)." (PMID 23028769, 2012). "CYP1B1 has also been implicated in juvenile and adult onset forms of glaucoma, in various ethnic groups worldwide." (PMID 21150032, 2011). "No consistent correlation has been observed between the severity of the glaucoma phenotype and the molecular CYP1B1 genotype among individuals with identical mutations within the same family, and among families with identical mutations." (PMID 22128238, 2011). "Mutations in the cytochrome P4501B1 (CYP1B1) gene have been reported to be associated with primary congenital glaucoma and other forms of glaucoma and mutations in pituitary homeobox 2 (PITX2) gene have been identified in ARS in various studies." (PMID 20827438, 2010). "This is the first study from north India reporting CYP1B1 mutations in Axenfeld-Rieger syndrome with bilateral buphthalmos and early onset glaucoma." (PMID 20827438, 2010). "The molecular association between PCG and JOAG or POAG has been documented in few cases with CYP1B1 mutations, but this is the first time that p.R390S has exhibited variable expressivity of glaucoma." (PMID 20664688, 2010). "In some studies, CYP1B1 mutations have been reported to be associated with primary open-angle glaucoma (POAG, OMIM 137760)." (PMID 20664688, 2010). "In our pedigree study, individuals carrying both the MYOC mutation and CYP1B1 variation were affected with juvenile glaucoma with goniodysgenesis." (PMID 19668597, 2009). "Although the mutations in CYP1B1 are the main known genetic cause of this type of glaucoma in different worldwide populations, the role of this gene in Spanish patients has not yet been investigated." (PMID 19234632, 2009). "The wide range of glaucoma phenotypes associated with CYP1B1 mutations suggests that it plays a key role in the physiology and development of the eye." (PMID 19234632, 2009). "However, patient 27 with CYP1B1 variants showed a different primary phenotype with diffuse corneal opacity and iris hypoplasia, while glaucoma was only diagnosed secondarily." (PMID 41155148, 2025). "The CYP1B1 c.1310C>T variant in pedigree RF.MA0499 may be associated with both glaucoma and retinal degeneration, suggesting a broader ocular phenotype." (PMID 40141357, 2025). "In addition, there is a need for more in-depth genotype–phenotype information, specifically the response to glaucoma surgeries for the more than 150 CYP1B1 variants." (PMID 40141740, 2025). "Notably, tricho-hepato-enteric syndrome 1 attributed to SKIC3 variants, exhibits a higher carrier rate in this population, while CYP1B1-related glaucoma presents with unique hotspot variants." (PMID 40421383, 2025). "In some cases, individuals may carry dual mutations, with one in the myocilin gene and another in the CYP1B1 gene, leading to a more aggressive and earlier-onset form of glaucoma." (PMID 38435218, 2024). "Lastly, CYP1B1 is implicated in metabolic pathways relevant to glaucoma." (PMID 38671671, 2024). "When CYP1B1 is mutated, the metabolic activity of E2 may be affected, leading to the upregulation of Myocilin and affecting the development of primary open-angle glaucoma (POAG)." (PMID 36704044, 2022). "In 33% of children with glaucoma mutations in the CYP1B1, FOXC1, LTBP2 and TEK genes were found." (PMID 35144644, 2022). "Therefore, screening for mutationsin CYP1B1 gene of children with early-onset glaucoma is advisable for early detection of PCG; such patients subsequentlyrequire special attention." (PMID 35087999, 2020). "Additionally, genome-wide association studies (GWAS) and other cellular techniques studying gene expression and regulation will undoubtedly change our understanding of how CYP1B1 mutations contribute to the pathogenesis of glaucoma and cancer." (PMID 32626511, 2020).
glaucoma (continued). "Additional studies in mice have demonstrated expression of Cyp1b1 in the trabecular meshwork, and heterozygosity of Cyp1b1 gene mutations has been associated with the presentation of juvenile onset glaucoma after the age of 2 years." (PMID 33425902, 2020). "Furthermore, scientists are investigating either CYP1B1 mutations or CYP1B1 overexpression since they contribute to glaucoma or cancer, respectively." (PMID 32626511, 2020). "In addition, we found an elevated frequency (8%) of heterozygous and rare PITX2 variants in the group of CG cases who were known to carry CYP1B1 glaucoma-associated genotypes, and one of these PITX2 variants arose de novo." (PMID 30657791, 2019). "Likewise, in this study we have found two glaucoma patients who carried heterozygous rare PITX2 and CYP1B1 variants and showed very early glaucoma onset and severe disease, characterised by a large number of surgical operations required to control IOP." (PMID 30657791, 2019). "CYP1B1 mutations cause ocular malformation and are a major cause of congenital and adult glaucoma." (PMID 29522511, 2018). "We found the recurrent p.Arg368His mutation of CYP1B1 in four independent families with glaucoma." (PMID 23922489, 2013). "Cytochrome P450, family 1, subfamily B, polypeptide 1 (CYP1B1) and myocilin, trabecular meshwork inducible glucocorticoid response (MYOC) mutations were identified in early-onset glaucoma in humans, whereas mutations in the CYP1B1 and FOXC1 were detected in mice with early-onset glaucoma." (PMID 23401651, 2013). "Mutations in CYP1B1 have been reported to cause glaucoma in a recessive trait." (PMID 23922489, 2013). "Here we tried to elucidate a possible underlying mechanism where regulation of 17β estradiol by CYP1B1 plays a key role in the cascade of events that may lead to glaucoma." (PMID 23028769, 2012). "Allele frequencies of the CYP1B1 cSNPs in primary open-angle glaucoma patients and controls." (PMID 18483560, 2008). "The haplotype analysis presented here show that identical mutated CYP1B1 alleles may be involved in the etiology of the various forms of glaucoma, suggesting that other genetic and/or environmental factors can affect the course of disease development." (PMID 19096718, 2008). "Moreover, there is no comprehensive study published to date that assesses the roles of three known glaucoma-causing genes (CYP1B1, MYOC, and OPTN) in the same set of Indian POAG patients." (PMID 17563717, 2007). "The CYP1B1 gene encodes a cytochrome p450 monooxygenase enzyme, and over 150 variants have been associated with a spectrum of eye diseases, including primary congenital glaucoma, anterior segment dysgenesis, juvenile open-angle glaucoma, and primary open-angle glaucoma." (PMID 40141740, 2025). "Moreover, obesity may be correlated with the pathogenesis of juvenile OAG, such as mutation of the CYP1B1 gene or the glaucoma-associated olfactomedin domain of myocilin." (PMID 34501469, 2021). "Cyp1b1's influence in the development and support of retinal ganglion cell structure and function under normal conditions or during stress, such as elevated ocular pressure; the most common risk factor in glaucoma, remains grossly unknown." (PMID 33748124, 2021). "However, the glaucoma phenotype could be less variable and therefore, more predictable in patients who carry completely inactive CYP1B1 alleles." (PMID 19234632, 2009). "A detailed STRING analysis with high confidence (0.900) uncovered a complex network indicating CYP1B1’s key role in primary congenital glaucoma development." (PMID 40821877, 2025). "The subsequent dissemination of genotype–phenotype data regarding CYP1B1-related eye diseases can help guide pediatric ophthalmologists and glaucoma specialists to best practices, especially regarding the choice of IOP-lowering surgery." (PMID 40141740, 2025).
glaucoma (continued). "Taking aniridia as an example, whilst PAX6 mutations remain the predominant cause, variants in CYP1B1, FOXC1, PXDN and SOX11 have also been reported in patients with childhood glaucoma and aniridia." (PMID 41011222, 2025). "Those rare variants are located in CYP1B1, SIX6, CARD10, MFN1, OPTC, OPTN, and WDR36 glaucoma-related genes." (PMID 38241218, 2024). "Through linkage analysis, 23 loci and four genes (MYOC/TIGR, CYP1B1, OPTN, and WDR36) had already been associated with glaucoma in the past years." (PMID 38241218, 2024). "Downregulated genes found to be targets of this miRNA include CYP1B1, which has been connected to ocular diseases such as glaucoma." (PMID 38674337, 2024). "Causative variants in CYP1B1 negatively impact its ability to metabolise 17β estradiol resulting in the overexpression of MYOC and can potentially lead to the development of glaucoma." (PMID 38755526, 2024). "Given the intimate relationship between CYP1B1 and glaucoma and the results observed in the first group, we sequenced the CYP1B1 gene in a different cohort of patients, detecting the variant p.Y81N in two more POAG patients." (PMID 38241218, 2024). "Variants in CYP1B1 (MIM number: 601771), associated with PCG and juvenile- or adult-onset primary open angle glaucoma (MIM: 231,300), were identified in 55% (11/20) of the solved families, and were either homozygous or compound heterozygous." (PMID 38755526, 2024). "While many studies reported the role of CYP1B1 in glaucoma and cancer, recent studies have indicated that CYP1B1 is involved in cardiac pathophysiological changes." (PMID 37848499, 2023). "CYP1B1, an AHR-inducible gene, is associated with various forms of glaucoma, including the two major types: primary open-angle glaucoma and primary congenital glaucoma." (PMID 35295218, 2022). "In secondary childhood glaucoma cases, alterations in CYP1B1 (25%), SOX11 (13%), FOXC1 (13%), GJA8 (13%) and LTBP2 (13%) were detected." (PMID 35011756, 2021). "Several of the differentially expressed genes have previously been reported to be associated with elevated IOP and/or glaucoma, including MYOC, ADAMTS10, LTBP2, LOXL1, TGFBR3, CYP1B1, and EFEMP15,28,43–45." (PMID 34385434, 2021). "Presently, TDRD7, CYP1B1, GJA1, IL1B, MMP1, and MMP3 have been considered as a causative gene for glaucoma." (PMID 33299458, 2020). "In the current study, we attempted to correlate retinol metabolism with glaucoma pathogenesis, especially with PCG, in a cell culture system through an extensive study with 23 CYP1B1 mutations." (PMID 27243976, 2016). "Mutations in CYP1B1 can infrequently underlie the autosomal dominant, juvenile open-angle glaucoma (JOAG, OMIM 137750) and even adult-onset forms of primary open-angle glaucoma (POAG, OMIM 137760)." (PMID 27484908, 2016). "Contrary to other known genes causing PCG (CYP1B1) or POAG (MYOC, OPTN, and WDR36), one can easily consider a plausible cellular and molecular basis for association between LTBP2 and the glaucoma phenotype." (PMID 23401661, 2013). "This suggests that CYP1B1 is the main known candidate gene causing PCG in our population, with a low or null contribution in other glaucoma phenotypes." (PMID 23922489, 2013). "To investigate the incidence of mutations in genes associated with the different phenotypes of glaucoma, we checked for mutations in MYOC and CYP1B1 in a large cohort of a Spanish population." (PMID 23922489, 2013). "Four genes, including trabecular meshwork inducible glucocorticoid response (MYOC), human dioxin-inducible cytochrome P450 (CYP1B1), optineurin (OPTN), and WD repeat domain 36 (WDR36), have been identified as glaucoma-associated genes." (PMID 22876119, 2012). "Mutations in CYP1B1 (GLC3A locus) have been found in PCG patients from different populations It is estimated that all known loci/genes of glaucoma account for the minority of total cases of glaucoma, and thus, many other genes remain to be identified." (PMID 20361014, 2010).